FBXW7 (F-box and WD repeat domain containing 7)
Diseases named in the same sentence as FBXW7 in open-access papers (continued):
Sharing a sentence is not in itself a finding about the gene and the disease.
cancer (continued). "Of 87 patients, 21 patients were analyzed by NGS with 48 selected cancer genes including GNA11, GNAQ and FBXW7, and 66 patients were analyzed for mutations by NGS with 592 cancer genes including BAP1 and SF3B1 mutations as well as MYC amplification." (PMID 34830903, 2021). "Our team has focused on investigating the functional role of FBXW7 in multiple cancers, including in CRC." (PMID 34217244, 2021). "Several studies have found FBXW7 deregulation in the host environment as one of the key determinants of cancer metastasis." (PMID 33822486, 2021). "Based on these few evidences, it is concluded that NOTCH and FBXW7 directly or indirectly involve in cancer metabolism, where TME and immune cells play a significant role." (PMID 33822486, 2021). "We found a rather narrow range of other genes (KMT2D, FBXW7, GNAS, ARID1A, NF1 and CTNNB1) harbouring mutations in 6–12% of the patients and a long tail of cancer genes with mutations in <6%." (PMID 34647903, 2021). "Among the E3 ligase proteins, the F-box and WD repeat-containing 7 protein (FBXW7) was particularly well-studied in cancer progression." (PMID 33800394, 2021). "Overall, the biology of FBXW7 is very complex not only in normal cells but in a wide range of carcinomas as well." (PMID 33822486, 2021). "In several cancer types, downregulation of FBXW7 was responsible for elevation of c-Myc and cancer progression." (PMID 32140077, 2020). "Several reseaches illustrated that FBXW7 plays critical roles in cancers by regulating Notch and mTOR." (PMID 32239181, 2020). "The most frequent cMDT among the COSMIC cancer genes were observed for the E3 ubiquitin-protein ligases FBXW7 and MDM2, and the Cyclin-Dependent Kinase CDK4." (PMID 32879328, 2020). "Altogether, our findings clarify the previously unrecognized role of FBXW7 in regulating the function of M2-like TAMs, and provide new potential target for anti-cancer therapies." (PMID 33260160, 2020). "Altogether, these results illustrate that FBXW7 knockout promotes M2 macrophage polarization and leads to the production of cancer-promoting factors by M2 macrophages." (PMID 33260160, 2020). "Collectively, these data demonstrate that FBXW7 knockout promotes cancer development by facilitating M2-like TAM polarization to modify the microenvironment." (PMID 33260160, 2020). "Accumulation studies demonstrated that FBXW7 played a significant role in cancer cells by autophagy." (PMID 32577098, 2020). "HSF1 accumulation due to altered expression of a substrate-targeting subunit of the SCF (Skp-1-Cull-F-box) ubiquitin ligase complex, FBXW7, provides an advantage in cancer cells during disease progression." (PMID 32457290, 2020). "And FBXW7 targets several proteins with critical roles in the hallmarks of cancer, such as cyclin E, Notch, mTOR, c-MYC, etc." (PMID 32239181, 2020). "Via targeting oncogenes for degradation, FBXW7 functioned as a tumor suppressor to attenuate uncontrolled cell proliferation and induced cell apoptosis in cancer cells." (PMID 32140077, 2020). "These mutants will be valuable to study the role of specific FBXW7-targeted oncoproteins in cancer progression and drug therapy resistance." (PMID 32907612, 2020). "The discovery of FBXW7 as a STAT2 stability regulator has deepened our understanding of the role of FBXW7 in human cancers." (PMID 32973222, 2020). "Further, EMT is one of the prime factors accountable for the initiation of chemoresistance and FBXW7 has been found to notably partake in regulating the EMT in cancer cells." (PMID 30791487, 2019).
cancer (continued). "Remarkably, the TCGA database indicates that both FBXW7 and SLC9A3 are commonly co-mutated with KRAS in human cancers." (PMID 31748650, 2019). "Having identified FBXW7 as a candidate gene worth exploring further, its yeast ortholog and expression in other cancers was investigated." (PMID 31351478, 2019). "This comprehensive review emphasizes on the targets, functions, regulators and expression of FBXW7 in different cancers and its involvement in sensitizing cancer cells to chemotherapeutic drugs." (PMID 30791487, 2019). "We further examined the effect of FBXW7 knockdown on the sensitivity to anti-cancer drugs using xenograft models." (PMID 31067777, 2019). "Studies have found that the anti-cancer activity of specific inhibitors of nuclear export (SINE) such as KPT-185 in Colo-357 PDAC xenografts is partly due to the accumulation of nuclear FBXW7 and subsequent degradation of Notch-1, c-Myc, and VEGF." (PMID 30791487, 2019). "The human FBXW7 gene is located at chromosome 4q31q.3, which is a region deleted in 30% of cancers, and consists of 4 untranslated and 13 coding exons." (PMID 30791487, 2019). "In CRC, FBXW7 represents an interesting therapeutic target in the light of its involvement in the regulation of several cancer-related pathways, including chemoresistance." (PMID 31569395, 2019). "We found that FBXW7 knockdown significantly increased the sensitivity to these anti-cancer drugs in the three CRC cell lines examined." (PMID 31067777, 2019). "This inhibition of FBXW7 resulted in upregulation of aurora kinase A which directs cancer cells proliferation and aggressive behavior of prostate SCNC." (PMID 30791487, 2019). "Many Fbxw7-related studies have therefore focused primarily on understanding of its role in cancer metabolism." (PMID 31371703, 2019). "Our study provided a novel strategy to reactivate FBXW7 in human cancer with LSD1 overexpression via targeting LSD1 protein for degradation, rather than merely inhibiting its enzymatic activity." (PMID 31342282, 2019). "The in vitro experiments revealed that knockdown of circ-FBXW7 promoted CRC cells growth, migration and invasion, but circ-FBXW7 overexpression reversed the cancer cell behaviors." (PMID 31519156, 2019). "Depletion of Pin1 results in up-regulation of FBXW7 and reduced levels of FBXW7 substrates such as Mcl-1, and sensitizes cancer cells to the chemotherapy drug Taxol." (PMID 30086763, 2018). "The E3 ligase FBXW7 suppresses cancer by reducing multiple oncogenes, but Pin1 inactivates FBXW7 by disrupting its dimerization and promoting its self-ubiquitination." (PMID 30158600, 2018). "At present, FBXW7 down-regulation is found in numerous human malignant tumors, including non-small cell lung cancer, T cells leukemia, bile duct carcinoma, pancreatic carcinoma and endometrial carcinoma." (PMID 28464881, 2017). "Given that NOTCH2, FBXW7 and DLL1 are key components in NOTCH signaling and have predictive value in cancer therapies, the effect of these mutations in NPC is yet to be elucidated." (PMID 28256603, 2017). "The study of FBXW7 is very important to understand the mechanism of tumorigenesis and to provide new targets for cancer diagnosis and treatment." (PMID 28149200, 2017). "F-box and WD repeat domain-containing 7 (FBXW7) is one of the most frequently perturbed proteins in the ubiquitin–proteasome system in cancer." (PMID 28829765, 2017). "FBXW7 has been identified in diverse human cancers, including T cell acute lymphoblastic leukemia, pancreatic cancer, endometrial cancer, and colon cancer." (PMID 28149200, 2017).
cancer (continued). "While the function of FBXW7 has been most thoroughly reported in cancer, FBXW7 has also been clearly shown to downregulate TLR4 (and inflammation) in human and murine macrophages by the Sterneck group." (PMID 27812198, 2016). "Elucidating its mechanism of action has become crucial for cancer therapy; however, it is also complicated by the fact that FBXW7 can influence many pathways due to its role as an E3-ubiquitin ligase in proteasome degradation." (PMID 25860929, 2015). "Taken together, these data demonstrated that FBXW7 regulates cancer cell EMT, motility and stem-like characteristics possibly via mTOR signaling in CCA cells." (PMID 25749036, 2015). "For example, FBxw7/Archipelago, a component of the SCF ubiquitin ligase complex that target cyclinE for degradation is mutated or inactivated in a variety of cancers." (PMID 25180228, 2014). "Because FBXW7 also participates in the cell cycle exit to, and the reentry from, the G0 phase, it is a candidate molecular therapeutic target in intractable carcinoma cases that are resistant to combined modality therapies." (PMID 25275295, 2014). "Our findings in this study suggest that differential expression of FBXW7α AS forms serves a new mechanism inactivating FBXW7 in human cancer." (PMID 23166673, 2012). "The gene FBXW7, which is deleted in many of our samples, influences murine intestinal homeostasis and cancer, targeting Notch, Jun, and DEK for degradation." (PMID 22879877, 2012). "Our results show that the transcriptional pattern of FBXW7 AS forms in human cancers is different from normal tissue compartment." (PMID 23166673, 2012). "Most important finding in this study is that the FBXW7 gene is deregulated through differential expression of AS forms in human cancers." (PMID 23166673, 2012). "We conclude that our Fbxw7R482Q/+ animals provide evidence that a ‘just right’ level of FBXW7 protein function is selected in many human cancers." (PMID 21503901, 2011). "We have just begun to understand the complex interplay between FBXW7/hCDC4, its target oncoproteins and other critical cancer genes." (PMID 21122106, 2010). "Furthermore, their work revealed the existence of a NICD/Hes-5/FBW7β positive feedback loop, which contributes to FBXW7 haploinsufficiency and underscores the intricate regulatory interplay between the Notch pathway and FBXW7 in cancer biology." (PMID 40534867, 2025). "In addition, the phosphorylation of FBXW7 at T205 through ERK1/2 activation induced the protein degradation of FBXW7 in cancer cells." (PMID 38892210, 2024). "The present study is the first to support the notion that K+ channel inhibition-mediated intracellular signaling may reduce cancer stemness by transcriptionally up-regulating the E3 ubiquitin ligase, FBXW7, in cancer spheroids with CSC properties." (PMID 38892210, 2024). "FBXW7 is down-regulated by oncogenic signaling pathways such as Akt in cancer cells." (PMID 38892210, 2024). "We previously identified FBXW7 as an essential regulator of KCa1.1 protein degradation in several cancers and showed that the down-regulated expression of FBXW7 by cancer spheroid formation increased KCa1.1 activity by promoting its protein level in the plasma membrane." (PMID 38892210, 2024). "Moreover, CHD4 was identified as a new substrate of FBXW7 in the regulation of cancer stemness in TNBC." (PMID 38268032, 2024). "Our previous studies indicated that FBXW7 negatively regulates cancer stemness in NSCLC cells." (PMID 38268032, 2024). "Thus, FBXW7 influences multiple malignant processes in cancer, particularly drug resistance, by regulating MCL-1 activity or expression levels." (PMID 39749199, 2024). "However, few studies have focused on the function of FBXW7 in cancer stemness in TNBC and the related mechanism." (PMID 38268032, 2024). "Currently, the cancer-related role of FBXW7 in TNBC is unclear." (PMID 38268032, 2024).
cancer (continued). "Interestingly, FBXW7 mRNA was upregulated in 10.68% in the same cancer type, and 31.68% in mature B-cell neoplasms, showing upregulation of the SCF complex in B-cell related cancers." (PMID 37760968, 2023). "FBXW7 was recently discovered to be a target gene for some miRNAs in various cancers." (PMID 37635248, 2023). "The loss of FBXW7 leads to stabilization and accumulation of SREBP1, which in turn triggers activation of AKT and enhances expression of target gene sets involved in cholesterol metabolism, thereby supporting cancer cell survival and proliferation." (PMID 37176148, 2023). "In addition, in vitro experiments also found that miR-32 transfected cells have lower expression of FBXW7 and higher expression of cancer-related proteins c-Jun and c-MYC." (PMID 36998461, 2023). "FBXW7 plays a role in regulating the immune system in cancer cells." (PMID 36998461, 2023). "Therefore, studies describing how FBXW7 is regulated are crucial for the development of anti-cancer therapies and future understanding of disorders that occur during development." (PMID 37183425, 2023). "Depletion of the E3 ligase FBXW7 sensitizes dormant cancer cells to paclitaxel, indicating that protein degradation may participate in the regulation of dormancy." (PMID 36694209, 2023). "FBXW7 expression regulates EMT in human cancers (Díaz and de Herreros, 2016)." (PMID 38027013, 2023). "This suggests that targeting FBXW7 in cancer treatment poses significant obstacles." (PMID 38027013, 2023). "Importantly, low expression of FBXW7 is correlated with invasion, metastasis and poor prognosis in a number of cancers." (PMID 37686662, 2023). "In addition, certain MicroRNAs have been reported to enhance cancer drug resistance via inducing FBXW7-mediated autophagy." (PMID 38027013, 2023). "Aberrant FBXW7 expression leads to cancer stemness and poor clinical outcome." (PMID 38027013, 2023). "Numerous miRNAs have been shown to target FBXW7 in various cells, tissues, and cancers." (PMID 35346215, 2022). "The functional activity of FBXW7 is important in hindering cancer growth." (PMID 36473865, 2022). "In addition, we are looking forward to incorporating additional hallmarks, continuing to explore FBXW7’s role in other facets of cancer." (PMID 35515121, 2022). "While each of these FBXW7-targeting miRNAs were discovered in individual cancers, it is still unknown whether they possess broad regulatory roles for FBXW7 expression in all cancers." (PMID 35346215, 2022). "FBXW7 expression presents a positive correlation of B-cell infiltration level in most cancers." (PMID 35814468, 2022). "The results shown here confirm our previous finding in CRC, highlighting that even in GBM, IPA and its synthetic analog N6-BA upregulate the expression and, indirectly, the activity of the oncosuppressor FBXW7 emerged in the last years as an appealing therapeutic target in different cancers." (PMID 35559231, 2022). "In addition, cancer-related mutations were found in P in 18 genes, including SMAD4 (11.9%), PIK3CA (11.9%), FBXW7 (9.5%), PTEN (7.1%), and BRAF (7.1%)." (PMID 35892888, 2022).
cancer (continued). "Here, we demonstrate the relative substrates of FBXW7 functioning in immunity in different cancers." (PMID 35814468, 2022). "For instance, FBXW7 is commonly identified as a tumor suppressor in various cancers." (PMID 35064108, 2022). "Therefore, FBXW7 expression is an independent prognostic biomarker of poorer outcomes in some cancers." (PMID 35346215, 2022). "SHOC2, a RAS/ERK activator and a substrate of FBXW7, selectively combines with Raptor to impede Raptor-mTOR binding and subsequent mTORC1 activity, contributing to the stimulation of autophagy and acceleration of cancer proliferation." (PMID 35515121, 2022). "In cancer, FBXW7 can inhibit macrophage M2-type polarization by mediating c-MYC degradation." (PMID 35346215, 2022). "F-box and WD repeat domain-containing 7 (FBW7) is a well-studied F-box-containing protein that functions as a cancer suppressor by targeting the oncoprotein substrate c-Myc for ubiquitination and degradation, thus regulating cell proliferation, apoptosis, and metabolism." (PMID 35884547, 2022). "In a retrospective CRC study, comparing cancer tissues and their paired adjacent non-cancerous tissues, FBXW7 expression was negatively associated with lymph node metastasis and TNM stages." (PMID 35346215, 2022). "All in all, FBXW7 functions discrepantly in immunotherapy of different cancers." (PMID 35814468, 2022). "The involvement of FBXW7 in immune evasion was also reported in cancer cells." (PMID 35814468, 2022). "As a frequently-mutated gene in cancers, we identified that FBXW7 was downregulated in HCC specimens compared with that of normal tissues." (PMID 34659544, 2021). "T1695 phosphorylation primes for FBXW7-mediated ubiquitination and degradation of Rictor, which may account for the overexpression of Rictor in cancers." (PMID 33670113, 2021). "We think that it might be because that FBXW7 is a central regulator in cancer biology mediating a diverse array of oncogenic processes." (PMID 35712679, 2021). "FBXW7 dysregulation is one means of tumorigenesis in various cancer types." (PMID 34954904, 2021). "In addition, several somatic variants in established cancer driver genes were identified, including driver genes of colorectal tumourigenesis, such as KRAS and FBXW7." (PMID 34843512, 2021). "Upregulation of FBXW7-185aa in cancer cells could repress proliferation and cell cycle acceleration, while knockdown of FBXW7-185aa could lead to cancerous phenotypes in vitro and in vivo." (PMID 33816529, 2021). "Collectively, these results suggest that a FBXW7-MYC-PLK1 signaling circuit underlies the tumorigenesis of MB and validate PLK1 inhibitors as potentially effective therapeutics for MYC-overexpressing cancers." (PMID 33494392, 2021). "Unlike DNA and histone methylation, m6A mRNA methylation that governs FBXW7 expression and/or function in cancers is largely unknown." (PMID 33676554, 2021). "FBXW7-mediated c-Myc degradation is also important for the maintenance of cell stemness, at least in hematopoietic stem cells, keratinocytes, and cancer stem cells." (PMID 32429232, 2020). "Taken together, these results demonstrated that LSD1 may negatively regulate FBXW7 for cancer cell survival in PCa cells." (PMID 33708617, 2020). "When FBXW7 expression was abrogated, its function in limiting M2 macrophage polarization was abolished, increasing the number of aberrant M2-like TAMs that can promote cancer development." (PMID 33260160, 2020). "FBXW7 can act as a monomer or a dimer, however dimerization is important for binding of protein with a weak CPD such as cyclin E. In cancer cells FBXW7 mutations are often heterozygote, which would allow the formation of homodimers for both wild type and mutated forms as well as heterodimers." (PMID 32907612, 2020). "Interestingly, SETD3 regulates the expression of other genes associated with cancer such as β-actin, FOXM1, FBXW7, Fascin, eNOS, and MMP-2." (PMID 32042016, 2020).